KCNJ6 (potassium inwardly rectifying channel subfamily J member 6)
Description:
Inward rectifier potassium channels are characterized by a greater tendency to allow potassium to flow into the cell rather than out of it. Their voltage dependence is regulated by the concentration of extracellular potassium; as external potassium is raised, the voltage range of the channel opening shifts to more positive voltages. The inward rectification is mainly due to the blockage of outward current by internal magnesium. This potassium channel may be involved in the regulation of insulin secretion by glucose and/or neurotransmitters acting through G protein-coupled receptors.
Synonyms: GIRK-2; GIRK2; KATP2; KCNJ7; Kir3.2; BIR1; hiGIRK2; KATP-2; KPLBS
Tractability: Small molecule: a high-quality ligand is known; it belongs to a druggable protein family. Antibody: its Gene Ontology location is reachable by antibodies, with high confidence; UniProt predicts a signal peptide or a membrane-spanning region. PROTAC: a small molecule that binds it is known.
Target class: Inwardly rectifying potassium channel; Potassium channels; Voltage-gated ion channel; Ion channel
Gene: Protein-coding gene on chromosome 21 (37,607,373 to 38,121,345, reverse strand). Ensembl gene ENSG00000157542.
Subcellular location: Membrane
Pathways (Reactome):
Neuronal System: Activation of G protein gated Potassium channels; Inhibition of voltage gated Ca2+ channels via Gbeta/gamma subunits
Gene Ontology:
Molecular function: inward rectifier potassium channel activity; protein binding; G-protein activated inward rectifier potassium channel activity
Biological process: potassium ion import across plasma membrane; potassium ion transport
Cellular component: Golgi apparatus; plasma membrane; voltage-gated potassium channel complex; membrane
Genetic constraint (gnomAD): Loss-of-function variants: 9 observed, 32.56 expected, observed/expected ratio (o/e) 0.28, 90% interval 0.17 to 0.48. The upper end of that interval is the gene's LOEUF score, 0.48, which puts it in group 2 of 6, group 1 being the genes least tolerant of losing a copy. Missense variants: 226 observed, 545.53 expected, observed/expected ratio (o/e) 0.41, 90% interval 0.37 to 0.46. Synonymous variants: 194 observed, 214.81 expected, observed/expected ratio (o/e) 0.9, 90% interval 0.8 to 1.02.
Homologues: Orthologues: macaque KCNJ6 (100% identical), dog KCNJ6 (99% identical), pig KCNJ6 (99% identical), mouse Kcnj6 (99% identical), rat Kcnj6 (99% identical), rabbit KCNJ6 (99% identical), guinea pig KCNJ6 (97% identical), tropical clawed frog kcnj6 (83% identical), zebrafish kcnj6 (80% identical), chimpanzee KCNJ6 (73% identical). Paralogues in human: KCNJ5 (70% identical), KCNJ9 (64% identical), KCNJ3 (52% identical), KCNJ2 (46% identical), KCNJ12 (45% identical), KCNJ4 (45% identical), KCNJ18 (45% identical), KCNJ14 (41% identical), KCNJ8 (40% identical), KCNJ11 (39% identical), KCNJ1 (36% identical), KCNJ16 (33% identical), and 3 more.
Diseases named in the same sentence as KCNJ6 in open-access papers:
KCNJ6 is named in the same sentence as 61 diseases in open-access papers, as found by Europe PMC text mining. Sharing a sentence is not in itself a finding about the gene and the disease. The quoted sentences say what the papers report.
Keppen-Lubinsky syndrome (10 papers, 2019 to 2025). "KCNJ6, which encodes a potassium ion channel protein that modulates dopaminergic neuron excitability, is associated with Keppen-Lubinsky syndrome." (PMID 40446031, 2025). "The region contains also KCNJ6 underlying Keppen-Lubinsky syndrome (OMIM #614098) characterized by severe ID, seizures and microcephaly." (PMID 33710394, 2021). "Whole exome sequencing (WES) identified a heterozygous pathogenic variant (c.460G>A; p.Gly154Ser) in the KCNJ6 gene, confirming a diagnosis of Keppen-Lubinsky Syndrome (KPLBS)." (PMID 41523402, 2025). "Thus, heterozygous mutations of KCNJ6, affecting the pore-forming domain of the GIRK2 channel, result in the Keppen-Lubinsky syndrome, a genetic disorder characterized by severe developmental delay, microcephaly, and intellectual disability." (PMID 36171878, 2022). "Keppen-Lubinsky Syndrome (KPLBS; OMIM #614098) is a severe neurodevelopmental disorder first delineated in 2015, resulting from heterozygous mutations in the KCNJ6 gene." (PMID 41523402, 2025).
Down syndrome (8 papers, 2013 to 2024). "On the other hand, overactive GIRK channels can also engender cognitive dysfunction, as demonstrated in a mouse model of Down syndrome, in which the mice carry an extra copy of the Girk2 gene (Kcnj6)." (PMID 35711474, 2022). "KCNJ6 (GIRK2) is a subunit of GIRK that is widely enriched in the brain and is associated with various functions and pathologies, including learning and memory, motor coordination, and Down syndrome." (PMID 39766283, 2024). "While KCNJ6 has no known direct association with AD, KNJC6 is associated with Down’s syndrome, which has a well-established increased risk for AD." (PMID 35883662, 2022).
Anxiety (6 papers, 2011 to 2024). Intense feelings of nervousness, tension, or panic often arise in response to interpersonal stresses. "Other potential mechanisms include genetic factors (e.g., catechol-O-methyltransferase (COMT) and potassium inwardly rectifying channel subfamily J member 6 (KCNJ6) genes), lipid markers, and psychological risk factors (anxiety and depression)." (PMID 38731944, 2024).
epilepsy (6 papers, 2011 to 2024). A brain disorder characterized by episodes of abnormally increased neuronal discharge resulting in transient episodes of sensory or motor neurological dysfunction, or psychic dysfunction. "Among those genes, Kcnj6 (Girk2) codes for a ion channel subunit, ion channels representing 66% of the currently known Mendelian human epilepsy gene, and a point mutation in this gene causes ataxia, tremor and tonico-clonic seizures in the weaver mouse." (PMID 22140471, 2011).
alcohol dependence (4 papers, 2019 to 2026). Physical and psychological dependence on alcohol. "A Kcnj6 variant has been linked to alcohol dependence in individuals exposed to psychosocial stress early in life." (PMID 36163074, 2022). "The Collaborative Study on the Genetics of Alcoholism (COGA) also identified a potassium channel gene KCNJ6 to be associated with endophenotypes of AUD56." (PMID 30718457, 2019). "KCNJ6 is also reported to be associated with alcoholism previously." (PMID 32093702, 2020). "Lending credence to the clinical significance of a GIRK-alcohol partnership, a SNP in the promoter region of the KCNJ6 gene, which encodes GIRK2, was found to be associated with adult alcohol dependence." (PMID 40903615, 2026).
breast carcinoma (4 papers, 2004 to 2024). "At present, most studies have shown that variations in the KCNJ6 gene are associated with persistent breast pain after breast cancer surgery, post-operative analgesia, and pain sensitivity." (PMID 39766283, 2024). "CPSP risk 6 months after breast cancer surgery has previously been reported for haplotype A2 rs3111020-rs11895478 G-A of KCNJ3 and rs2835925 of KCNJ6." (PMID 33868360, 2021).
cognitive deficits (4 papers, 2017 to 2022). "In contrast, KCNJ6 has been implicated in several genetic abnormalities characterized by cognitive impairment, as well as in the modulation of a variety of higher brain functions." (PMID 36171878, 2022). "KCNJ6 may also play an important role in the generation of infantile spasms associated with cognitive impairment, as well as in other disorders." (PMID 36171878, 2022). "Overexpression of KCNJ6 impairs synaptic plasticity and provokes cognitive impairment resembling DS in wild type mice." (PMID 36171878, 2022). "Regarding the cognitive deficits, several ion channels, such as Kcnj13 or Kcnj6, and ion channel modulators were deregulated in the present screen." (PMID 30013462, 2018). "Thus, KCNJ6 abnormalities may influence brain development and lead to cognitive impairment, supporting the notion that triplication of this gene plays an important role in cognitive impairment in DS." (PMID 36171878, 2022).
developmental delay (4 papers, 2021 to 2024). "The gene mutations are associated with severe developmental delay, facial dysmorphism and mental retardation, reduced cognitive ability (KCNJ6, NALCN)." (PMID 35205240, 2022).
Intellectual disability (3 papers, 2022 to 2024). "While many discoveries link their importance to behavioral phenomena, mutations in KCNJ6 (GIRK2) or KCNJ13 (Kir7.1) result in severe cranial-facial malformations along with intellectual disabilities." (PMID 38527087, 2024).
asthma (2 papers, 2018 to 2022). "Moreover, KCNJ6 is also upregulated in mild and severe asthma in peripheral blood cells." (PMID 35033200, 2022). "There were common genes between these two study groups, where five genes were up-regulated (ATP5E, BRK1, KCNJ6, RNASEH2C, and RPL9) and one gene (RAB5B) was down-regulated in patients with mild and severe asthma compared with normal individuals." (PMID 30038057, 2018).
nicotine dependence (2 papers, 2017 to 2022). Physical and psychological dependence on nicotine. "Human gene polymorphism analysis revealed that the rs2835859 SNP in the KCNJ6 gene, which encodes the GIRK2 subunit, was associated with nicotine dependence." (PMID 36289814, 2022). "SNPs in Kcnj6 (GIRK2) have been linked to alcohol and nicotine dependence, reduced opioid withdrawal and increased opioid requirement for analgesia." (PMID 28676630, 2017).
alcohol use disorders (1 paper, 2024). "SNPs in noncoding regions of KCNJ6 were linked to frontal inhibitory control in individuals with alcohol use disorders and were found to reduce GIRK2 expression level and increase cellular excitability." (PMID 38903913, 2024).
bipolar disorder (1 paper, 2015). A disorder of the brain that causes unusual shifts in mood, energy, activity levels and the ability to carry out day-to-day tasks. "We identified three rare deletions in KCNJ6, UNC13C, OTOL1 and 7 rare duplications in CNTNAP2/MIR548F3, CORO7/VASN, DTNB, EMID2, KCNF1, PDPR and SGTA/THOP1 that are present in children with bipolar disorder (and their parents)." (PMID 25887117, 2015).
cognitive decline (1 paper, 2018). "In particular, several Kcnj6 “pain risk” alleles are known to date, and neuroprotective roles of GIRK channels are emerging, supporting a potential contribution of Kcnj6 downregulation in the cognitive decline of FD patients with age." (PMID 30013462, 2018).
congenital cataracts (1 paper, 2023). "Patient #3 had a deletion in chromosome 21, including the RUNX1, DYRK1A, and KCNJ6 genes, classified as likely pathogenic as variants in DYRK1A have been associated with bilateral congenital cataracts." (PMID 36980880, 2023).
Crohn disease (1 paper, 2022). A gastrointestinal disorder characterized by chronic inflammation involving all layers of the intestinal wall, noncaseating granulomas affecting the intestinal wall and regional lymph nodes, and transmural fibrosis. "The cg20515679 probe from KCNJ6, which was associated with post-FEV1/FVC, has also been associated with Crohn's disease and NO2 according to EWASatlas." (PMID 35033200, 2022).
T-cell lymphoma (1 paper, 2016). "The proximal protein coding genes included LTA4H (leukotriene A4 hydrolase) on chromosome 12, TIAM1 (T-cell lymphoma invasion and metastases) and KCNJ6 (potassium channel, inwardly rectifying subfamily J, member 6) both on chromosome 21." (PMID 26959888, 2016). "rs2660852 flanked 5′UTR of LTA4H (leukotriene A4 hydrolase), rs477145 was intronic to TIAM1 (T-cell lymphoma invasion and metastases) and rs2835931 was intronic to KCNJ6 (potassium channel, inwardly rectifying subfamily J, member 6)." (PMID 26959888, 2016).
cancer (7 papers, 2005 to 2025). A tumor composed of atypical neoplastic, often pleomorphic cells that invade other tissues. "This is the first association study on polymorphisms in KCNJ6 and response to methadone for pain management in advanced cancer." (PMID 36261449, 2022). "The aim of this study was to determine any association of KCNJ6 rs2070995 with opioid requirements and therefore contribution to inter-individual variability in response to methadone for pain management in patients with advanced cancer." (PMID 36261449, 2022). "Clinical, demographic, psychological, cancer treatment-related variables, quantitative sensory testing, and patient genotype (COMT, OPRM1, GCH1, ESR1, and KCNJ6) were assessed as risk factors using multiple logistic regression." (PMID 37184910, 2023). "Polymorphisms in the KCNJ6 gene affect pain responses by modifying the function of GIRK2 channels that regulate opioid receptors, leading to changes in pain tolerance and opioid efficacy and affecting treatment outcomes and quality of life for cancer patients." (PMID 40075716, 2025).
KCNJ6 also shares sentences with these, for which no sentence is quoted: infection (6 papers); respiratory depression (4); depression (3); Parkinson disease (3); Alcoholism (2); Ataxia (2); lipodystrophy (2); microcephaly (2); neurological disorder (2); schizophrenia (2); acquired lipodystrophy (1); Atypical progeroid syndrome (1); Autoimmunity (1); Cerebellar hypoplasia (1); channelopathies (1); diabetes (1); Dravet syndrome (1); Epileptic spasm (1); familial partial lipodystrophy (1); genetic disorder (1); glioma (1); gynecological cancers (1); holoprosencephaly (1); hyperkinetic disorder (1); Hypertension (1); infantile spasms (1); lung carcinoma (1); multiple lipomatosis (1); Neonatal progeroid syndrome (1); neurodevelopmental disorder (1).
A further 13 diseases each share a sentence with KCNJ6 in 1 paper.